CD4 (CD4 molecule)
Diseases named in the same sentence as CD4 in open-access papers (continued):
Sharing a sentence is not in itself a finding about the gene and the disease.
tumor (continued). "One approved therapy for bladder cancer, an extract of the Mycobacterium bovis strain Bacille Calmette Guerin, which is locally instilled into the bladder, has been shown to induce T helper 1 (TH1) CD4+ T cell responses against the tumour and to provide long-term protection in mice." (PMID 37198490, 2023). "It was reported that lung epithelial cells and splenic CD4+ T cells have the ability to synthesize and secrete ACh, therefore, the influence of chronic stress on the synthesis of ACh in epithelial cells and CD4+ T cells in the lung of tumor-bearing mice was examined." (PMID 37773152, 2023). "Specifically, the presence of tumor-infiltrating lymphocytes (TILs), T cell (CD4+, CD8+, NK, γδ), macrophages, dendritic cells (DCs), B cells, mast cells, and neutrophils, as well as their localization, formation and density, can influence both the immune response and patient survival." (PMID 37251324, 2023). "In addition, preclinical analysis of murine tumors has demonstrated that the administration of CD4-LV exerts a faster and higher caliber killing of tumor cells than CD8-LV administration alone or in combination with CD4-LV." (PMID 38328405, 2023). "Finally, 13 patients (28.3%) showed a low CD4/CD8 ratio in the tumor tissue, in comparison to 33 out of 46 (71.7%) that had a high ratio." (PMID 37373171, 2023). "However, as the tumor progresses, the neoplastic cells become able to escape the immune activity of CD4+ T cells by modifying their surface antigens." (PMID 37631922, 2023). "The present study suggests that GCDs led to increased infiltration of CD4+ T cells in the tumor and a decreased presence of regulatory T cells, suggesting an increased immunity in the tumor microenvironment and consistent with the role of ferroptosis in the tumor microenvironment." (PMID 36969027, 2023). "CD4 T cells subclustered into five distinct groups with divergent localizations between blood and tumor; clusters 1, 3 and 5 were more prevalent in blood, while clusters 2 and 4 were almost exclusively present in tumor." (PMID 37487666, 2023). "Furthermore, introduction of Helicobacter hepaticus increases tumor infiltration by cytotoxic lymphocytes and the anti-tumor immunity is dependent upon CD4+ T cells and NK cells." (PMID 37143538, 2023). "As the key enzyme catalyzing the conversion of OAA into PEP, PCK1 overexpression could elevate PEP levels in T cells under glucose-limited conditions to enhance the anti-tumor effect of tumor-specific CD4+ T cells." (PMID 37250903, 2023). "Furthermore, the “Gene” module analysis revealed that the mRNA RECK level was remarkably relevant to tumor purity, B cells, CD4+ T cells, dendritic cells, macrophages, CD8+ T cells and neutrophils." (PMID 37255541, 2023). "In addition, it was negatively correlated with follicular helper T cells, CD8+ T cells, memory-activated T cells CD4+, activated NK cells, resting mast cells, B-cells, plasma cells that have the function of tumor killing or to inhibit." (PMID 37779109, 2023). "However, CD4+ T cells activated by PADRE(X) would be unable to contribute to antitumor immunity by any mechanism requiring tumor specificity after relaying T cell help." (PMID 37655661, 2023). "However, a recent study suggests that CTLA4 and PD1 blockade therapy inhibit tumor growth via CD4+ T cells." (PMID 36969495, 2023). "Furthermore, these results suggest that other effector functions of CD4+ T cells requiring tumor specificity are dispensable in this model." (PMID 37655661, 2023). "The staining suggested that CD4+ CTLs were in contact with HLA-DR-positive tumor cells." (PMID 38077321, 2023). "However, the presence of chronic stress has been observed to result in an elevation of CD4+T cells within tumor tissues, thereby potentially facilitating the differentiation of cancer stem cells." (PMID 38089966, 2023).
tumor (continued). "Additionally, the expression of these co-inhibitory receptors has been detected in tumor-infiltrating CD4/CD8 Teff cells and Tregs which are also involved to create tumor evasion." (PMID 36109471, 2023). "TIM-3 would also have a specific inhibitory role in antitumour immunity: it is, indeed, widely expressed on tumour antigen-specific T lymphocytes, both at the peripheral blood level and at the level of tumour-infiltrating lymphocytes (TILs), either CD4+ or CD8+." (PMID 36980583, 2023). "This provides strong evidence that LRRC3B might play an essential role in tumor inhibition facilitated through CD4+/CD8+ T cells." (PMID 36798137, 2023). "Thus, we leveraged our MPS to evaluate the effect of CD4 T cells on multiple key aspects of the ML-NK cell response, including ML-NK cell extravasation, tumor penetration, and cytotoxicity in a more physiologically relevant scenario." (PMID 37865647, 2023). "Furthermore, the combination of the anti-CCR5 antibody with an anti-PD-1 antibody treatment decreased the tumor burden in mice, correlating with increased tumor infiltration of CD4+ and CD8+ T cells." (PMID 37759462, 2023). "Functional CD4+ cells could play a major role in the anti-tumor response induced by TOP2A vaccine treatment." (PMID 37880313, 2023). "Furthermore, recently discovered primary human lung apCAFs from ATII can directly prime TCRs for tumor infiltrating CD4 + T cells, which not only enhances anti-tumor immunity but also protects against apoptosis." (PMID 37723510, 2023). "Similarly, we observed that CD4+ Tregs were closer to stromal cell types, which helps explain spatial segregation of the CD4+ Tregs away from Productive T cell & Tumor CNs in 2HC T cell-treated tumors." (PMID 38085642, 2023). "The T-cell 2NBDG assay suggests that in the tumour both CD4+ and CD8+ T cells maintain their glycolysis even after ex vivo culture, and thus may support anti-tumour responses in vivo." (PMID 37660049, 2023). "Tumor specificity of CD4+ T cells and provision of help to CD8+ T cells." (PMID 37655661, 2023). "Additionally, subsets of CD4+ T cells also combat tumors through various mechanisms including direct killing of tumor cells and regulation of inflammation within the microenvironment." (PMID 37744350, 2023). "CD4+ CD25+ Tregs inhibit CD8+ T cell-mediated tumor rejection." (PMID 36814928, 2023). "Overall, these finding suggest that redirecting pathogen-specific CD4+ CTL towards tumor cells could be a promising mean to enhance the efficacy of immunotherapies." (PMID 37965314, 2023). "Therefore, it is possible that methionine was deprived from CD4+ T cells by tumor cells, leading to decreased levels of activated CD4+ T cells." (PMID 37179124, 2023). "Besides, the infiltration of macrophages, antigen-presenting cells (APCs), CD4 + T cells, dendritic cells (DCs), and other tumor-infiltrating immune cells was significantly correlated with the BC prognosis." (PMID 37875600, 2023). "Further, FAP-based WCTV could have significant anti-tumor properties, slowing tumor growth and reducing the recurrence rate by eliciting host immune response in which antigen-specific cytotoxic T cells and CD4+ T lymphocytes participate." (PMID 37316886, 2023). "Also, primary stroma-rich CRC tumors had fewer infiltrating immune cells, and preoperative suppression of tumor-specific CD4+ T-cells was correlated with patient relapse." (PMID 37207219, 2023). "Indeed, Vps34 inhibition induces the infiltration of NK, CD8+, and CD4+ T effector cells to the tumor microenvironment." (PMID 37443821, 2023). "In MHC-deficient HCmel12 Jak1-KO tumours, CD4+ T cells showed no changes in their migratory behaviour in the stroma and a slightly increased motility in the tumoural compartment of the invasive margin." (PMID 37316667, 2023).
tumor (continued). "This suggests that concomitant activation of CD4+ T cells by a neoantigen vaccine platform not only improves priming of CD8 epitope responses but also plays a vital role in optimizing the trafficking of neoantigen-specific CD8+ T cells into the tumor." (PMID 38063199, 2023). "Particularly, compared to the tumor microenvironment (TME) of the low-risk group, the TME of the high-risk group included considerably more regulatory cells (Tregs), M1 macrophages cell, natural killer cell, B cell, activated CD8 and CD4 T cell." (PMID 37543772, 2023). "Interestingly, multiple immunofluorescences analysis indicated a strong positive correlation between IGSF6 expression and tumor-infiltrating lymphocytes, including CD4+ and CD8+ T cell, in CRC tumors." (PMID 37989761, 2023). "As already mentioned, PD-L1 signaling on CD4+ memory cells by cross-linking was demonstrated to evoke highly suppressive cells, however the expression of PD-L1 on immune cells can on the other hand be predictive of response in some tumor entities." (PMID 36776340, 2023). "It would be worthwhile to elucidate whether the binding of RNase1 to EphA4 on CD4+ T cells stimulates their migration to tumor tissue for maintaining immune homeostasis." (PMID 37416781, 2023). "CD4+ T cells can exert their anti-tumor effects through various mechanisms." (PMID 37509488, 2023). "Indeed, Treg depletion improves the capacity of CD11b+ DCs to trigger CD4 T-cell responses, leading to a better control of the tumor." (PMID 37190135, 2023). "However, S15+ TAMs were spatially closer to CD4+FoxP3+ Tregs than S15− TAMs, and S15+ tumor cells in distinct ranges." (PMID 37674198, 2023). "More studies are needed to characterize which antigens may be presented directly by MHC-II+ tumor cells under what conditions to fully understand the context-dependent roles of CD4+ T cells in cancer." (PMID 36512410, 2023). "In mice xenografted with cervical tumors and treated with ATRA and PDL1 Ab, MDSCs were diminished and tumor growth decreased, presumably mediated by high intra-tumoral infiltration of CD4+ and CD107a+CD8+ cytotoxic T-cells and the production of pro-inflammatory cytokines (IFNγ, TNFα)." (PMID 37686465, 2023). "However, the specific mechanisms underlying changes in phenotypes and immunosuppressive functions of CD4+CCR8+ Tregs recruited into tumor tissues are still unclear and need to be further studied." (PMID 37950246, 2023). "In the HCC tumor microenvironment, M2-TAMs promote tumorigenesis by enhancing proliferation, invasion, metastasis, and angiogenesis; they also suppress anti-tumor immunity by inhibiting the functions of CD4+ T cells and CD8+ T cells." (PMID 38264642, 2023). "It is also important to note that other immune cells in the CT26 tumor microenvironment such as CD4+ T helper cells may have contributed to the expansion of low avidity tumor-specific CD8+ T cells in the presence of anti-PD-1." (PMID 37586767, 2023). "In our study, we closely examined the tumor microenvironment by immunofluorescence staining of immune cells, such as CD4+ helper T lymphocytes, CD8+ T lymphocytes, NK cells and F4/80 macrophages, as well as presence and distribution of blood vessels and Ki-67+ proliferating cells." (PMID 37304301, 2023). "Therapies bolstering the function of CD4+ T cells, like immune checkpoint blockade, could also induce a positive effect through normalization of the tumor vasculature." (PMID 37440925, 2023). "verified that radiotherapy combined with anti-CD25/CTLA4 monoclonal antibody could reduce Tregs, PD1+CD8+ and PD1+CD4+ T cells and effectively mount the anti-tumor response, inhibiting the growth of local and distal unirradiated tumors." (PMID 37124519, 2023). "However, most CD39+ CD8+ T cells are trapped in the tumor stroma where we see highest frequencies of CD39+CD4+ T cells and CD73+ stromal cells and therefore likely undergo adenosine mediated immunosuppression." (PMID 37648263, 2023).
tumor (continued). "Cytotoxic CD8+ T, CD4+ T, and NK cells work together to maintain immune surveillance, whereas the abundant immune cells in HCC, such as MDSC, Tregs, and tumor-associated macrophages, help the immune evasion to accelerate tumor progression." (PMID 37954858, 2023). "Canonical Wnt signaling also inhibits Treg activity; therefore, suppression of Wnt by tumor-derived DKK3 may mediate CD4+ cell differentiation toward Tregs." (PMID 37847565, 2023). "Thus, the therapeutic utility of Tr1-like CD4+ CAR T cells in balancing tumor killing with mitigation of cytokine release syndrome would be worth exploring." (PMID 37654482, 2023). "Their study found that a considerable proportion of these neoantigens were immunogenic and were restricted by a large number of MHC-II molecules, which could be identified by CD4+ T cells and have an anti-tumor effect." (PMID 37415744, 2023). "Moreover, CD4-CD8- cells were observed to be less and CD4 + CD8+ cells more abundant in all tumor groups compared to the control population." (PMID 38092866, 2023). "Moving one step forward, adoptively transferred CD70-expressing immature DCs could prime CD8+T-cells, by CD27, to become tumor-eradicating cytolytic effectors and memory cells with a capacity for robust secondary expansion, independently of CD4+T-helpers." (PMID 37345056, 2023). "M2-like tumor-associated macrophages (TAM, CD206hiCD11b+F4/80+) have been demonstrated to elicit Treg accumulation in TME either through Treg recruitment by chemotaxis or peripheral Treg stimulation from naive CD4+ T cells." (PMID 37875481, 2023). "The reason for this discrepancy remains unclear, but it may be because the function of CD4 + T cells within the tumor microenvironment—i.e." (PMID 37277702, 2023). "Interestingly, selective deletion of MHC II in cDC1s can prevente early activation of CD4+ T cells by tumor-derived antigen." (PMID 37183207, 2023). "In LUAD, multiple T-cell subsets (CD8+, CD45RO+, CD8+CD45RO+ and CD4+FoxP3+) showed closer proximity to tumour cells than in LUSC, which exhibited closer distances from tumour cells to T-cells expressing LAG-3, OX40 and TIM-3, and B-cells expressing OX40 and LAG-3." (PMID 37835491, 2023). "In addition to its well-acknowledged activity in inducing type I IFN production by myeloid cells, the STING pathway can modulate tumor immunity by regulating the differentiation of CD4 T cells." (PMID 37189417, 2023). "Given the higher functional diversity of CD4+ cells, it could be assumed that this higher promiscuity is a characteristic of this cellular subtype and is reflected in the tumor context through the observation of a greater number of motifs." (PMID 37600765, 2023). "Therefore, we evaluated the abundance of intratumoral CD4+ Treg cells in CD1d−/− mice nourished with the control or WTMCGEP diet on day 28 after the tumor challenge." (PMID 37152373, 2023). "Moreover, CD4+PD-1− T cells migrated closer to the tumor cells, while CD4+PD-1+ T cells moved even farther away from the tumor cells under the combination treatment." (PMID 37275884, 2023). "One review concluded that CD4+ T cells in the TME have dual anti-tumor and pro-tumor effects." (PMID 37965307, 2023). "Given the observation that CLTCH129>Q-specific CD4+ T cells could contribute to primary tumor immunity, we investigated the potential of TCR-engineered T cells to limit tumor burden in the context of therapeutic ACT against large established tumors." (PMID 37400675, 2023). "Accordingly, the adoptive transfer of IFN-γ-activated eosinophils into the lungs of tumor-loading mice promoted the infiltration of CD4+ and CD8+ T cells, while pharmacological depletion of regulatory T cells in a tumor model induced evident eosinophilia, which facilitated antitumor immunity." (PMID 37508545, 2023).
tumor (continued). "CD4+T cells participate in the anti-tumor immune response by secreting various cytokines and chemokines to recruit inflammatory cells and help activate CD8+T cells, while CD8+T cells mainly exert immunocidal effects through the perforin–granzyme pathway and the Fas-FasL pathway." (PMID 37513021, 2023). "In addition, the adenylate cyclase catalytic product cAMP upregulates the inhibitory molecule CTLA-4 on the surface of CD4+ T cells, which enables tumor cells to evade immune surveillance by T cells and continue to develop." (PMID 36979847, 2023). "However, combination treatment with CD5-2 and anti-PD1 led to higher CD4+ T cell counts in the adjacent non-tumor tissue compared to other groups (except the CD5-2 + anti-PD1 control group)." (PMID 37795103, 2023). "When evaluating the percentage of CD4 and CD8 T cells out of total tumor cell numbers, there was a significant increase of both CD4- and CD8-positive cells in tumors of mice treated with the combination of Poly(I:C)+ OX40+ TIM-3 when compared to those treated with PBS (p < 0.05)." (PMID 37046612, 2023). "Although anti-PD1 antibodies primarily target T cells, B and CD4+ T cells were essential in ICB-driven anti-tumor responses via secreting antibody and helping T cell response, as indicated by depletion of B cells significantly reduced therapeutic response to anti-PD1 in mice model." (PMID 37231145, 2023). "Mouse tumor studies have provided important insights into tumor-specific CD4 CTL functions." (PMID 37185301, 2023). "We therefore addressed whether tumor cell conditioned media could influence the differentiation of naïve CD4+ T cells in vitro." (PMID 36883731, 2023). "Similarly, patients who had higher levels of expanded CD4+ or CD8+ Th1-like immune cells had an improved pathologic response to treatment with lower tumour regression scores." (PMID 37359545, 2023). "Besides, we also analyzed the proportion of CD3+CD4+T cells in tumors and found that the tumor bearing mice treated with glycosylated-PEG-oHSV contained a relatively higher percentage of CD3+CD4+T cells compared to tumors treated with PBS or oHSV alone." (PMID 37908722, 2023). "Also, high levels of RANK and RANKL were found in the tumor samples and correlated with lower disease-free survival, while the T cells markers (CD4+ and CD8+) and the immune checkpoint PD-1/PD-L1 were poorly detected in the samples." (PMID 36831348, 2023). "However, recent research has shown that CD4+ T cells, particularly CD4+ memory T cells, are crucial for the immunotherapy-induced tumor regression." (PMID 38090588, 2023). "In addition, the Wilcoxon rank-sum test demonstrated that high-risk score groups have a higher level of immune cells in the tumor microenvironment, such as B cells memory, T cells CD4 memory resting and mast cells activated." (PMID 37014321, 2023). "Consistently, the tumor infiltrated CD4+ or CD8+ T cells were increased in the nigericin-treated and combination therapy groups, suggesting that nigericin-mediated pyroptosis modulated the tumor microenvironment to facilitate the T cell infiltration, thus turning cold tumors into hot tumors." (PMID 37370831, 2023). "CD4 + T cells’ primary role is to mediate the anti-tumor immunity by stimulating CD8 + T cells." (PMID 37264091, 2023). "Also, six immune cell types (B cells, CD8+ T cells, CD4+ T cells, macrophages, neutrophils, and dendritic cells) and tumor purity were analyzed using the Tumor IMmune Estimation Resource (TIMER1.0) (Tumor IMmune Estimation Resource (TIMER2.0)." (PMID 36798137, 2023). "Therefore, it is possible that antigen-specific CD4 T cells induced by ITI-3000 vaccination exhibit direct cytolytic activity in the B16-LT tumor model." (PMID 37711623, 2023). "As angiogenesis is one of the ways that tumours are able to evade detection by the immune system, we hypothesized that PD1hi CD200hi CD4+ exhausted T cells might contribute to immunotherapy resistance by promoting angiogenesis." (PMID 37313656, 2023).